CSF1 (colony stimulating factor 1)
Diseases named in the same sentence as CSF1 in open-access papers (continued):
Sharing a sentence is not in itself a finding about the gene and the disease.
tumor (continued). "One of the objectives of nano-delivery of drugs is to control the tumor-associated macrophages (TAMs), triggered by chemokines and other growth factors (e.g. colony-stimulating factor-1) provided by tumor cells to the mass of the tumor." (PMID 36051855, 2022). "In fact, metastasized primary BC had higher tumor epithelial and stromal expressions of CSF-1 (p < 0.001 and p = 0.002, respectively) and CSF-1R (both p = 0.03) compared to non-metastatic cancers." (PMID 36294305, 2022). "Depletion of CSF-1/CSF-1R was shown to significantly inhibit tumour progression and metastasis in various tumour models." (PMID 36131942, 2022). "MDSCs, recruited by tumour secreted CSF1 and CSF2, suppress T cells including CD8+, NK cells, DCs and macrophages." (PMID 35445563, 2022). "This αKG- HIF1α cascade upregulates PD-L1 and colony-stimulating factor-1 (CSF1), which further increase HCC metastasis via infiltration of tumor associated macrophages (TAMs) and myeloid derived suppressor cells (MDSCs)." (PMID 35280777, 2022). "A recent study demonstrated a cross talk between tumor cells and tumor-associated macrophages (TAMs) via SIGLEC1, CCL8, and CSF1, suggesting that the gene signature of TAMs correlated with poor clinical outcomes." (PMID 35223504, 2022). "Altogether, the data indicates that UHRF1 promotes tumor cell CSF1 production, which in turn assists macrophage tumor trafficking and activation." (PMID 35664070, 2022). "Pretreatment with trametinib interfered with the interaction between the malignant cells and the microenvironment via reducing tumor-derived CSF-1." (PMID 35292516, 2022). "Polarization of TAMs toward the M2 phenotype is driven by the CSF1 (mainly secreted by tumor cells)/CSF1 receptor (CSF1R) axis." (PMID 35315360, 2022). "BRD4 inhibition was also shown to decrease M2 tumor-associated macrophage (TAM) proliferation, particularly by directly inhibiting HIF1α expression in tumor cells, thereby inhibiting the secretion of M2-promoting colony-stimulating factor 1 (CSF1)." (PMID 36139513, 2022). "Previous studies have suggested that many chemokines (CCL5 and CCL2) and cytokines (the VEGF family members and CSF‐1) can be able to recruit circulating inflammatory monocytes to the tumor environment, exerting an enormous effect on the formation of TAMs." (PMID 35593325, 2022). "Tumor cells release chemo-attractants such as colony-stimulating factor 1 (CSF-1) and the chemokine C-C motif chemokine ligand 2 (CCL2) to recruit monocytes that differentiate into M2 macrophages." (PMID 36297535, 2022). "Taken together, our results suggest that increased TAMs, and specifically M2 population, were attributed to TAb2 tumor-derived CSF1 and VEGF." (PMID 35366939, 2022). "induced forced expression of the macrophage colony-stimulating factor 1 receptor (CSF-1R) to render CAR-T cells sensitive to CSF1, a monocyte recruiting chemokine enriched in various tumor tissues." (PMID 35211124, 2022). "In particular, macrophage chemoattractant molecules [e.g., C-C Motif Chemokine Ligand 2 (CCL2)/monocyte chemoattractant protein 1 (MCP-1), colony-stimulating factor 1 (CSF-1)] play a major role to recruit TAMs into the tumor microenvironment." (PMID 35327359, 2022). "Although multiple experimental mAbs have shown evidence of target specificity, characterised by increased serum CSF-1 and reductions in M2-associated CD163+, CD206+, and CSF-1R+ TAMs, insufficient anti-tumour activity has been displayed." (PMID 35020853, 2022). "Colony stimulating factor 1 (CSF1) produced by tumor cells promotes differentiation of TAMs and production of granulocyte-specific chemokines in CAFs." (PMID 36532071, 2022). "CSF1 acts as a tumour-promoting cytokine by recruiting macrophages to the tumour area, which in turn leads to the release of various tumour-promoting growth factors in the microenvironment." (PMID 35860566, 2022).
tumor (continued). "Monocytes and macrophages from the bone marrow and spleen can respond to tumor-derived factors, such as CSF-1, and initiation of the CSF-1R signaling cascade results in their proliferation, differentiation, and migration to the tumor." (PMID 35821822, 2022). "Tumour infiltrating monocytes are predominantly Ly6Chigh and can be recruited via CSF-1/CSF-1R signaling." (PMID 35821822, 2022). "In recent years, targeting TAM therapies such as CSF-1 or CSF-1R blockade have attracted extensive attention in tumor research." (PMID 35814365, 2022). "Mechanistically, haloperidol stimulates the production of colony-stimulating factor 1 (CSF-1) on tumor cells by activating nuclear factor kappa B (NF-κB), and its downstream autocrine oncogenic CSF-1 receptor signaling contributes to this carcinogenesis." (PMID 35804859, 2022). "Pexidartinib (PLX3397) is a multi-kinase inhibitor targeting CSF-1R that is FDA approved for the treatment of tenosynovial giant cell tumor, a rare CSF1-driven neoplasm." (PMID 36077755, 2022). "Downregulation of CSF-1 expression and arrest of tumor cell proliferation resulted in an immune-active TME, which is required for immunotherapy efficacy." (PMID 35292516, 2022). "In contrast, prolonged treatment with trametinib abolished the antitumor activity of αPD-1, because tumor cells undergoing the epithelial to mesenchymal transition in response to trametinib restored CSF-1 expression and recreated an immune-suppressive TME." (PMID 35292516, 2022). "On the contrary, restoration of CSF-1 expression can accelerate tumor progression and metastasis in a CSF-1 mutant mouse xenograft model." (PMID 36131942, 2022). "Tumor stroma contains several cell types capable of producing CSF-1, such as endothelial cells and fibroblasts." (PMID 36555673, 2022). "Overexpression of colony-stimulating factor-1 (CSF-1) in tumor cells was used to show the effect of tumor-derived CSF-1 on sensitivity to trametinib and anti-programmed death- 1 (αPD-1) in mice." (PMID 35292516, 2022). "Inhibition of CSF-1/CSF-1R signaling reduced the tumor-infiltrating MDSCs and enhanced the anti-tumor T cell responses." (PMID 35585567, 2022). "They provided scenarios of tumor reduction or elimination by decreasing the secretion of CSF-1, EGF, the density of macrophages, chemotaxis sensitivity, and increasing the degradation of CSF-1 or EGF." (PMID 36439180, 2022). "We considered the specimens to have CSF1 rearrangement if a split signal was observed in greater than 2% of the tumor cells." (PMID 36320082, 2022). "Meanwhile, macrophages release epidermal growth factor (EGF), which enhances tumor cell invasion and migration, and further stimulates tumor cells to secrete CSF-1, thus forming a positive feedback loop between tumor cells and macrophages." (PMID 35965509, 2022). "Accordingly, higher expression of CCL2 and CSF1 were observed in tumor samples of CREBBPmut patients than those of CREBBPwt patients by RNA sequencing." (PMID 33431788, 2021). "Other cytokines secreted by the tumor cells, including CSF1 and TGF-β also strongly promote M2-polarization of TAMs." (PMID 34771482, 2021). "A variety of growth factors secreted by many tumor cells, such as CSF1, CSF2, and VEGF, are also involved in regulating the fate of the MDSC in the TME." (PMID 34858479, 2021). "Release of CSF-1 from tumor cells promotes recruitment and survival of macrophages within the TME, and these cells, in turn, promote tumor cell migration via release of macrophage-derived epidermal growth factor." (PMID 33924237, 2021). "In a model of metastatic PDAC refractory to anti-PD-1 checkpoint blockade, inhibition of CSF-1-mediated release of granulin from TAMs prevented fibrosis and restored anti-tumor immune responses, leading to reduced metastatic burden." (PMID 33924237, 2021).
tumor (continued). "Consistent with this, in metastatic PDAC, tumor-cell-derived CSF-1 induces macrophages to produce granulin, a secreted glycoprotein that promotes fibroblast activation and spurs tumor growth." (PMID 34729112, 2021). "Currently, inhibition of CSF-1/CSF-1R interaction by therapeutic antibody to deplete TAMs and their pro-tumor functions is becoming a prevalent strategy in cancer therapy." (PMID 33805444, 2021). "TAMs are recruited to the tumor site by colony-stimulating factor-1 (CSF-1/M-CSF) to enhance their survival, differentiation and proliferation." (PMID 33922795, 2021). "CSF1 expression in tumor cells has been previously shown to be related to higher proportions of TAMs in GBM." (PMID 34011400, 2021). "Tenosynovial giant cell tumors (TGCTs), for example, are a rare and locally aggressive type of tumor characterized by high levels of CSF-1 and overexpression of CSF-1R+ macrophages." (PMID 34178692, 2021). "For example, the deletion of PI3Kγ improved survival and responsiveness to standard-of-care chemotherapy in animal models of PDAC, and the dual inhibition of PI3Kγ and CSF-1/CSF-1R reduced the tumor infiltration of MDSCs and inhibited tumor growth." (PMID 34356110, 2021). "Meanwhile, TAM blocking by the CSF-1 receptor inhibitors or CSF-1 antibodies can break prostate cancer resistance and reverse tumor progression in mammary tumors." (PMID 34281293, 2021). "In the tumor microenvironment, tumor cell-derived CSF1 is enriched within peri-tumoral tissues and functions as a chemoattractant to recruit circulating monocytes, subsequently resulting in increased macrophage infiltration." (PMID 34248982, 2021). "TREM2 is expressed on CSF1R+ TAMs and is modulated by CSF1 and its blockade on TAMs results in delayed tumor growth, remodeling of the tumor immune contexture and increased ICI efficacy." (PMID 34220848, 2021). "Tumor cells can secrete colony stimulating factor-1, chemokine (C-C motif) ligand 2 (CCL2), chemokine (C-C motif) receptor 5 (CCR5), chemokine (C-X-C motif) ligand 1 (CXCL1), and so on, to recruit immunosuppressive myeloid cells toward the TME." (PMID 34948368, 2021). "EZH2 inhibition in tumor cells of MCS increases the expression of CSF-1 that, beyond enhancing TAM accumulation, is a crucial TME signal skewing their differentiation toward an M2 phenotype." (PMID 33922336, 2021). "Here, we show that MARCO+ macrophages appear to be recruited from the blood via the upregulation of a set of factors secreted by tumor cells, including CSF1 and TGF-β." (PMID 34011400, 2021). "CSF1 from senescent tumor cells enhance monocyte differentiation into M2 macrophages, which inhibit CD8+ T cell activation." (PMID 33643790, 2021). "This analysis showed that tumour-derived M-CSF (gene name CSF1) is the main contributor to moMac differentiation." (PMID 33627655, 2021). "Exosomes in hypoxic tumor areas contain large amounts of chemokines and immunomodulatory proteins, including CSF-1, CCL2, FTH, FTL, and TGF-β, which promote the differentiation of infiltrating myeloid cells toward an M2-like macrophage lineage." (PMID 34603327, 2021). "Though clinical data on the treatment efficiency of repolarizing agents is limited, it is clear that CD47-SIRPα, CD40/CD40L, and CSF-1/CSF-1R molecular pathways are involved in tumor survival and progression." (PMID 34988021, 2021). "Then, RT-qPCR was performed to measure the expression levels of GAPLINC, miR-135b-5p and CSF1 in tumor tissue specimens from engrafted nude mice." (PMID 34722262, 2021). "Recruitment of MDSC in the TME aid in this suppression of TH immune cells, where TNF-α, IL-1, IL-6, colony stimulating factor 1 (CSF-1), IL-8, IL-10, and type I interferons can also play a role in the regulation of TH immune response to tumor cells." (PMID 34012451, 2021).
tumor (continued). "Blocking the CSF-1/CSF-1R axis can not only directly treat tumor cells with CSF1R, as a targeted therapy, but also can promote the polarization of TAM and improve the tumor microenvironment, thereby exerting an anti-tumor effect." (PMID 34729112, 2021). "TAMs that originate from circulating monocytes are recruited to the hypoxic tumor area by tumor-derived factors, such as colony-stimulating factor-1 (CSF-1), VEGF-A, and chemokine (C–C motif) ligand 2 (CCL2)." (PMID 33230600, 2021). "CSF-1 has been described as the most important tumor-derived factor leading to monocyte recruitment through CCL2/CCR2 interaction, so CCR2 blockade therapies have been effective in suppressing TAM recruitment." (PMID 34209703, 2021). "Preclinical studies have shown that the CSF-1/CSF-1R signaling cascade not only decreases the number of infiltrating TAMs but also repolarizes M2-like to M1-like phenotypes within the tumor microenvironment." (PMID 33802565, 2021). "In the future, immunohistochemistry staining of CSF-1 on TAMs from paraffin embedded tumor tissue should be addressed." (PMID 33805444, 2021). "In B-lymphoma murine models, xenografted tumors bearing CREBBP/EP300 mutation presented lower H3K27 acetylation, higher M2 macrophage recruitment, and more rapid tumor growth than those with CREBBP/EP300 wild-type control via FBXW7-NOTCH-CCL2/CSF1 axis." (PMID 33431788, 2021). "In 63–77% of patients with TGCT, a minority of the neoplastic tumor cells show a CSF1 translocation, with COL6A3 being the most common fusion partner." (PMID 33799327, 2021). "In the blood circulation and tumor microenvironment, CSF-1 regulates the migration and function of these cells." (PMID 33537102, 2021). "Mechanistically, circASAP1 functions as a sponge for miR-326 and miR-532-5p and enhances the expression of CSF-1 and MAPK1, resulting in an increase in intra-tumor infiltration of tumor associated macrophages and activation of the MAPK-ERK signaling pathway." (PMID 33959506, 2021). "CSF-1 participates in the recruitment of TAMs to tumor tissues and the M2 polarization process of TAMs." (PMID 34683963, 2021). "In turn, PyMT cells secrete CSF1, which binds the CSF1 receptor on macrophages promoting their taxis towards the tumor cells." (PMID 33235291, 2021). "Studies have shown that some neutralizing antibodies or inhibitors targeting chemokine systems (CXCR4, CXCR2, and CCL2) and tumor-derived factors (CSF1, GM-CSF, and IL-6) can inhibit the expansion or recruitment of MDSC." (PMID 34447750, 2021). "Even though macrophage reprogramming using CSF1R inhibitors or CSF1 antibodies has been achieved for anti-tumor therapy, their effectiveness is still uncertain in most cancers." (PMID 34248982, 2021). "Taking together all the results, withholding of the M-CSF supplement dramatically augments pro-tumor activity of M2 macrophages through endogenous CSF-1 activation and its downstream genes reprogramming." (PMID 33805444, 2021). "Under hypoxia, tumor cells release a chemoattractant, which we take to be macrophage colony stimulating factor-1 (CSF-1), that establishes a spatial chemotactic gradient as it diffuses through the spheroid." (PMID 34625491, 2021). "At the same time, Clony stimulating factor-1 (CSF-1) produced by tumor cells can promote macrophages to secrete more EGF, which in turn can promote the production of tumor CSF-1." (PMID 33391402, 2021). "The colony stimulating factor-1 signaling pathway induced by osteopontin can destroy the transport of tumor-related macrophages and make HCC sensitive to anti-PD-L1 blockade." (PMID 33714200, 2021). "Tumor cells frequently overexpress some cytokines, such as macrophage colony-stimulating factor 1 (CSF-1) and monocyte chemoattractant protein-1, (MCP-1), which recruit a large number of macrophages into tumor sites." (PMID 35070992, 2021).
tumor (continued). "SET domain bifurcated 1 (SETDB1) is upregulated in GBM and promotes AKT/mTOR-dependent CSF-1 induction and secretion, which leads to macrophage recruitment in the tumor, resulting in tumor growth." (PMID 34071306, 2021). "Blocking the CSF-1-CSF-1R axis inhibits the polarization of macrophages, thereby reducing tumor cell proliferation and inducing TAM apoptosis." (PMID 34683963, 2021). "In summary, this study provides the first evidence that miR-148b-5p acts as a tumor suppressor miRNA, and that miR-148b-5p deficiency induces GC development and immune tolerance via the miR-148b-5p/ATPIF1/TNFa plus IL6 and CSF1 axis." (PMID 33717068, 2021). "K2 enhances TGF-β-induced production and secretion of Colony Stimulating Factor-1 (CSF-1), which stimulates macrophage chemotaxis into the tumor microenvironment as well as their polarization to the M2 immunosuppressive phenotype." (PMID 35936112, 2021). "These mice showed tumor growth like wild-type (+/op/PyMT) animals but had slower tumor progression and decreased invasion and metastasis consistent with the requirement for CSF-1 signaling for invasion and metastasis." (PMID 34207035, 2021). "For example, macrophages, one of the most represented categories of cells in the tumor microenvironment, are recruited by different soluble factors produced by the tumor, such as CSF1 (colony stimulating factor 1) and IL6 (Interleukin-6)." (PMID 33926496, 2021). "TAM-membrane-coated nanoparticles with conjugated photosensitizer (NPR@TAMM) and CSFR not only consumed tumor-derived CSF1, but also induced M2 macrophages transform into M1 via photodynamic immunotherapy." (PMID 34717710, 2021). "CSF-1, a significant growth factor involved in this process, helps recruit macrophages to the tumor site, promoting tumor progression to malignancy." (PMID 33613850, 2021). "The role of macrophages in tumor progression and metastasis was highlighted using a null mutant of CSF1, a macrophage growth factor." (PMID 33235291, 2021). "By contrast, during tumor progression there is a subversion of macrophage functions, from M1 to M2, due to many factors, including the presence of IL-4 synthesized by CD4+ T cells and tumor cells and of tumor-derived GF such as CSF1 and GM-CSF." (PMID 33920505, 2021). "In the second loop, CCL5 secreted from MSCs activates BCCs via CCR5, which promotes the BCCs to secret CSF1 and further recruits TAMs and MDSCs to the tumor region." (PMID 33849537, 2021). "On the other hand, inhibition of CSF-1 signals lowered the number of circulating cancer cells and tumor metastasis in vivo." (PMID 34207035, 2021). "A study determined that after primary tumor site irradiation, expression of macrophage colony-stimulating factor 1 (CSF1) increased significantly both in patients and preclinical prostate models." (PMID 34768644, 2021). "Similar to ROS induced senescent tumor cells, CSF1 and CSF1/CXCL12 overexpressing cells induced the upregulation of CD206 and showed an increased expression of the mRNAs associated with M2 macrophages." (PMID 33643790, 2021). "Here, we summarized the biological functions of CSF-1/CSF-1R and reviewed cancer promoting mechanisms regulated by CSF-1/CSF-1R axis in neoplasms, particularly in gastrointestinal tract malignant tumors." (PMID 34729112, 2021). "In summary, withholding of CSF-1/CSF-1R interaction would rather augment than suspend the M-CSF-driven pro-tumor activities of M2 macrophages in a long run." (PMID 33805444, 2021). "CSF1 downregulation by shCSF1 in ROS induced senescent tumor cells decreased M2 macrophage differentiation." (PMID 33643790, 2021). "Gene expression analysis reveals increased expression of C‐X‐C motif chemokine ligand 12 (CXCL12) and colony stimulating factor 1 (CSF1) in senescent tumor cells." (PMID 33643790, 2021). "CSF‐1 phosphorylation facilitates macrophage proliferation and conversion to TAMs, as well as tumor cell invasion and metastasis." (PMID 34027092, 2021).